RN7SL621P (RNA, 7SL, cytoplasmic 621, pseudogene)
Gene: Miscellaneous RNA gene on chromosome 8 (33,580,210 to 33,580,508, reverse strand). Ensembl gene ENSG00000240189.
Homologues: Orthologues: chimpanzee Metazoa_SRP (98% identical), macaque Metazoa_SRP (94% identical). Paralogues in human: RN7SL2 (83% identical), RN7SL1 (83% identical), RN7SL3 (82% identical), RN7SL326P (80% identical), RN7SL478P (80% identical), RN7SL769P (80% identical), RN7SL230P (80% identical), RN7SL679P (80% identical), RN7SL143P (79% identical), RN7SL556P (79% identical), RN7SL127P (79% identical), RN7SL147P (79% identical), and 701 more.